STAT3 (signal transducer and activator of transcription 3)
Diseases named in the same sentence as STAT3 in open-access papers (continued):
Sharing a sentence is not in itself a finding about the gene and the disease.
melanoma (continued). "One of the important findings of the present study is that targeting STAT3 by either pharmacological inhibition with STAT3 inhibitor C188-9 or shRNA-mediated depletion suppresses oncolytic NDV-primed expression and release of ICD markers in melanoma cells." (PMID 31192135, 2019). "For this reason, it is important to note that suppression of STAT3 activity disrupts B-RAF V600E-mediated induction of antiapoptotic proteins, seriously affecting the survival of melanoma cells." (PMID 30999681, 2019). "Poly (ethylene glycol)-b-poly (L-lysine)-b-poly (L-leucine) (PEG-PLL-PLLeu) polypeptide micelles was used for co-encapsulating Toll-like receptor agonist, STAT3 siRNA and OVA antigen to generate nanovaccine in OVA-transfected melanoma cell line." (PMID 30847297, 2019). "Expression of STAT3 and STAT3 response genes was reduced when prostate (DU145), breast (SCK), and melanoma (B16) cell lines were treated with STAT3 antisense oligonucleotides." (PMID 31671769, 2019). "To evaluate the antitumor effect of STAT3 siRNA on melanoma in vivo, we delivered PEI/siRNA topically to B16F10 melanoma tumor-bearing mice by dissolving MNs." (PMID 29348670, 2018). "The loss of SOCS1 expression leads to the activation of the JAK2/STAT3 signaling pathway and overexpression of MMP-2, FGF2, and VEGF and enhanced invasion and angiogenesis of melanoma cells, consequently promoting brain metastasis." (PMID 30285793, 2018). "OC also inhibited the STAT3 upstream activator, Janus kinase 2 (JAK2), and Src kinase signalling in melanoma cell apoptosis." (PMID 29734791, 2018). "Knockdown of c-Jun resulted in decreased levels of PD-L1 in melanoma cells resistant to BRAF inhibitors, and co-activation of STAT3 and the subsequent formation of a transcriptional complex further enhanced these effects." (PMID 29765155, 2018). "Notably, the IL-7-induced expansion of IL-17-producing γδ T cells in B16-F10 melanoma is abolished by STAT3 inhibition, and the inhibition of IL-23-induced expansion of antigen-induced γδ T cell subsets in tubercolosis correlates with dicreased expression and phosphorylation of STAT3." (PMID 29316631, 2018). "In conclusion, our study demonstrates that melanoma cell-secreted exosomal miR-155 can trigger normal fibroblast reprogramming into proangiogenic CAFs by decreasing SOCS1, to activate JAK2/STAT3 signaling pathway." (PMID 30285793, 2018). "In our study, treatment with melanoma cell-secreted exosomes significantly elevated the phosphorylation levels of JAK2 and STAT3 in CAFs." (PMID 30285793, 2018). "A375 cells stably expressing STAT3C, a constitutively active STAT3 mutant, were used to determine the role of STAT3 signaling in SLE’s anti-melanoma effects." (PMID 28596565, 2017). "These pathways including ERK1/2, STAT1, STAT3, STAT5, AKT and mTOR are known to drive the tumoral progression in melanoma cells and are found to be crucial in the interactions of melanoma with its microenvironment and progression to metastasis." (PMID 28223541, 2017). "In melanoma cells, we also found that SLE obviously suppressed the phosphorylation of STAT3 (Tyr 705) and Src (Tyr 416), which is consistent with the results of our animal experiments." (PMID 28596565, 2017). "As indicated by the data set of Talantov melanoma, compared with normal controls, the expressions of FAK, Src, ERK1/2 and Stat3 are up-regulated, while the expression of PPARγ is down-regulated in metastatic melanoma." (PMID 28108732, 2017). "In melanoma A375, G361 and B16F10 cells, the phosphorylation of STAT3 at the tyrosine 705 (Tyr705) site was dose-dependently inhibited by apigenin." (PMID 26911838, 2016). "In this regard, it is plausible to postulate that apigenin inhibited melanoma invasiveness by decreasing MMP-2 activity and expression through suppressing the constitutively active STAT3." (PMID 26911838, 2016). "Constitutive STAT3 activation has been reported to up-regulate VEGF expression and stimulate melanoma tumor angiogenesis." (PMID 26911838, 2016).
melanoma (continued). "STAT3-dependent reciprocal regulation of IL-23 and IL-12 was demonstrated in melanoma (B16), bladder (MB49), and colon (MB38) cancer models and targeting STAT3 in reduced tumor growth in vivo." (PMID 27148255, 2016). "In this study, we evaluated the anti-melanoma activities of IT, and determined the cytotoxic mechanism through IGF-1R/STAT3 pathway." (PMID 27323414, 2016). "Gene expression analysis revealed top pathways (T cell trafficking, communication, and differentiation) and top upstream regulators (CD3, CD28, IFNG, and STAT3) that significantly changed with age in 84 IMCG and 43 TCGA primary melanomas." (PMID 27760559, 2016). "Therefore, directly inhibit Stat3 might be a promising novel approach for melanoma therapy." (PMID 26830149, 2016). "In summary, we reported that IT exerted anti-melanoma activities, and these effects were partially due to inhibition of FASN/IGF-1R/STAT3 signaling." (PMID 27323414, 2016). "Hono treatment decreases the phosphorylation of Akt, signal transducer and activator of transcription 3 and ERK2 in colon cancer, malignant melanoma, and SVR endothelial tumors." (PMID 27074557, 2016). "Thus, regulation of STAT3 activity may enhance the efficacy of melanoma therapy." (PMID 25671570, 2015). "Therefore, we tested whether fad104 regulated the phosphorylation level of STAT3 in melanoma cells." (PMID 25671570, 2015). "It is reported that the inhibition of STAT3 activity by JSI-124 (cucurbitacin I), an inhibitor of STAT3, suppressed tumor growth of B16F10 melanoma cells." (PMID 25671570, 2015). "In human melanoma cells, 6-bromoindirubin-3′-oxime inhibits JAK and STAT3 signaling and 7-bromoindirubin (designated as MLS-2438) inhibits STAT3 and Akt signaling, with both derivatives inducing apoptosis." (PMID 26457112, 2015). "MiR-17 inhibits melanoma growth by stimulating CD8+ T cells mediated host immune response, which is due to its regulation of STAT3." (PMID 25594054, 2014). "STAT3 has been shown to increase HIF-1α levels by extension of protein half-life but also induction of HIF-1α transcription in human and mouse melanoma cells." (PMID 24743777, 2014). "Although in vivo findings showed only weak interaction between DBD-1 and STAT3 DNA binding domain, DBD-1 can induce significant apoptosis in murine melanoma B16 cells." (PMID 24743778, 2014). "To test the relevance of this observation in melanoma, particular in melanoma patients, we genotyped PBL and melanoma cell lines for STAT3 rs4796793 SNP and subsequently measured the STAT3 mRNA expression these." (PMID 25593920, 2014). "The group concluded that downregulation of STAT3 and pSTAT3 by HDI in melanoma and host immune cells is central to the immunomodulatory effect of IFN-α." (PMID 24516470, 2014). "Accordingly, STAT3 and STAT5 have become interesting potential target molecules for the treatment of melanoma." (PMID 23693134, 2013). "Similar conclusions were drawn from a study by Tekle and his colleagues, which proved that B7-H3 contributed to the metastatic capacity of melanoma cells by modulation of MMP-2 and signal transducer and activator of transcription 3 (Stat3)." (PMID 23940627, 2013). "Niu and coworkers reported that constitutive activation of STAT3 upregulates VEGF expression and tumor angiogenesis in melanoma cells." (PMID 24199193, 2013). "Furthermore certain features found more often in melanoma cells in the brain compared to their extracranial counterparts, such as STAT3 (regulates a number of prosurvival genes) or heparanase (increases tumor invasiveness) could be exploited by the drug development community." (PMID 24455677, 2013). "In three different human melanoma cell lines, SK-MEL-13, -28, and -37, IL-27 induced tyrosine phosphorylation of STAT1 and STAT3, indicating that these cells were responsive to IL-27." (PMID 24155891, 2013).
melanoma (continued). "These compounds reduced basal STAT3 phosphorylation (pSTAT3), and induced apoptosis in four separate human RCC cell lines and in human melanoma cell lines as determined by Annexin V/PI staining." (PMID 22899991, 2012). "Significantly, SOID-8 inhibits IL-6-induced STAT3 and JAK2 activation in melanoma cells, further supporting this notion." (PMID 23166634, 2012). "The Janus kinase-2 (Jak2)-signal transducer and activator of transcription-3 (STAT3) pathway is critical for promoting an oncogenic and metastatic phenotype in several types of cancer including renal cell carcinoma (RCC) and melanoma." (PMID 22899991, 2012). "In this study, we have discovered that the spirooxindole derivative SOID-8 inhibits melanoma cell proliferation and induces apoptosis of melanoma cells at least in part due to inhibition of the JAK2/STAT3 signaling pathway, in vitro and in vivo." (PMID 23166634, 2012). "One small molecule inhibitor of p-STAT3 with excellent CNS penetration, WP1066, has demonstrated antitumor effects in a murine model of melanoma, including against melanoma within CNS." (PMID 22488042, 2012). "The STAT3 pathway is an emerging oncogenic target in the setting of RCC, melanoma, and other forms of cancer." (PMID 22899991, 2012). "SOCS1 overexpression led to activation of STAT3 signaling and increase of MMP-2, and SOCS1−high melanoma cells enhanced invasive properties." (PMID 23231923, 2012). "A more probable explanation for these results is the high constitutive activity in other signalling pathways that also drive melanoma cells through the cell cycle, such as PI3K/Akt and Src/STAT3." (PMID 17245336, 2007). "Inhibition or silencing of STAT3 reduced GPR161 expression and impaired melanoma cell growth." (PMID 41834581, 2026). "In BRAF mutant melanoma cells, DHT suppresses the STAT3/SOX2 signaling pathway." (PMID 39944829, 2025). "Like IL6/STAT3, genetic and pharmacological targeting of GLI1 showed that IFNγ/STAT1 requires functional GLI as a second signal for the full-blown induction of IDO1 in human melanoma cells." (PMID 39962447, 2025). "In BRAF-mutant melanoma cells, inhibition of the MAPK pathway may promote signal transduction and transcription activator 3 (STAT3) reactivation." (PMID 39944829, 2025). "Similarly, inhibition of HDAC6 suppresses M2 polarization through STAT3 inactivation, thereby reducing tumor burden in SM1 melanoma and humanized NSG-SGM3 mouse models." (PMID 41008624, 2025). "Furthermore, in our study, we showed that neutrophil-derived STAT3 is upregulated in solid human tumors, such as HNC or melanoma, and it is correlated with poor disease outcomes." (PMID 40885734, 2025). "Additionally, it can decrease melanoma cell viability and colony formation by inhibiting the JAK2/STAT3 pathway and downregulating BCL-xL, further triggering apoptotic cell death." (PMID 41463545, 2025). "JAK/STAT3 signaling plays a pivotal role in the oncogenesis, progression, and maintenance of CSCs in skin cancers, with its activation being crucial for the formation of SCC, BCC, and melanoma." (PMID 40399946, 2025). "Indeed, we discovered significantly elevated expression of STAT3 in tumors compared with paired normal mucosa tissue (for HNC) and normal skin (for melanoma) (respectively)." (PMID 40885734, 2025). "TRIM14 has been shown to promote melanoma malignancy via the PTEN/PI3K/AKT and STAT3 pathways." (PMID 40593126, 2025). "Notably, STAT3 and STAT1 were among the top-ranked targets, further supporting the potential involvement of the JAK-STAT signaling pathway in MBP’s anti-melanoma activity." (PMID 40508400, 2025). "Furthermore, by controlling the STAT3 pathway, DHA treatment significantly accelerated the mitochondrial apoptosis of melanoma." (PMID 38397437, 2024). "Notably, the administration of dexamethasone has been observed to elevate both STAT3 and the pro-survival factor PI3K levels within melanoma cells, consequently leading to an increase in STAT3 levels." (PMID 38319731, 2024).
melanoma (continued). "Inhibition of the JAK kinases, NF-κB and STAT3 with small molecule inhibitors, and siRNA mediated knockdown of STAT1 and IRF1 was applied to investigate the molecular mechanism behind IFNγ induced PD-L1 expression in dedifferentiated melanoma cells." (PMID 39736644, 2024). "Thus, our experimental setting provides a mechanistic model to derive the immune response in melanoma patients and emphasizes the prognostic and therapeutic benefit of disrupting the E2F1 and/or STAT3 coregulator interaction and its networks." (PMID 39544930, 2024). "In cultured human melanoma cells, FYN kinase has been shown to phosphorylate STAT3 on Tyr705." (PMID 39641161, 2024). "In melanoma, UPR activation catalyzes tumor cell proliferation via the IL-6/STAT3 axis." (PMID 39080273, 2024). "It has been demonstrated that luteolin exerts antimelanoma effects in vitro and in vivo without overt toxicity to normal cells and also in melanoma-bearing mice through the suppression of STAT3 signaling via binding to SRC protein." (PMID 39234106, 2024). "Similarly, in melanoma, HDAC8 participates in the transcriptional regulation of PD-L1 by interacting with the transcriptional complex of HOXA5 and STAT3, thereby inhibiting PD-L1 expression." (PMID 38762484, 2024). "We also observed increased p-STAT3 levels in melanoma BMICs upon HLA-G overexpression, signifying that HLA-G activation of STAT3 signaling is not restricted only to lung BMICs." (PMID 36780531, 2023). "ATL I inhibits cancer cell proliferation and induces apoptosis primarily by regulating the PI3K/Akt, JAK2/STAT3, TLR4/MyD88/NF-κB, Notch, and ERK/GSK3β signaling pathways to treat colon, gastric, lung, melanoma, ovarian, breast, bladder, leukemia, prostate, and cervical cancers." (PMID 37241729, 2023). "The compound also downregulated the levels of Akt, STAT3, and MAPK in melanoma cells." (PMID 36675015, 2023). "Meanwhile, GL incubation effectively reduced the expression of Treg specific markers (Forkhead Box P3, glucocorticoid-induced TNFR-related protein and cytotoxic T lymphocyte antigen 4), phospho-STAT3, COX-2 and prostaglandin E2 in melanoma cells, finally limiting the progression of melanoma." (PMID 37649893, 2023). "Melanoma-derived factors, namely leukemia inhibitory factor (LIF), controlled JunB upregulation through Janus kinase (JAK)/signal transducer and activator of transcription 3 (STAT3) signaling." (PMID 37894348, 2023). "In order to further validate these results, we employed the IL-6/JAK/STAT3 pathway inhibitors αIL-6R, Baricitinib (JAK inhibitor, Amadis Chemical) and Stattic (STAT3 Inhibitor, Sigma-Aldrich), and determined their effect on the melanoma-microglia crosstalk." (PMID 37296634, 2023). "In addition to MITF, we screened several potential molecules that mainly affect certain melanoma characteristics, including RAS, MITF, PI3K, NF-κB, and STAT3." (PMID 37575275, 2023). "Furthermore, inhibition of STAT3 decreased the expression of GDF15, and GDF15 silencing increased the sensitivity of melanoma cells to sunitinib." (PMID 36720918, 2023). "Melanoma cells led to a reduction of lipid content in CAAs, possibly by downregulation of lipid synthesis pathways (lower FADS, SC4MOL, FASN) or enhancement of lipolysis (higher level of phosphorylation of ERK and STAT3)." (PMID 37481560, 2023). "The melanoma cell‐secreted sEVs could activate CAFs through the elevation of the phosphorylation levels of JAK2 and STAT3 in CAFs." (PMID 37171030, 2023). "Moreover, the treatment of the melanoma cells with the mimetic AnxA1 N-terminal peptide Ac2–26 stimulated the invasiveness by increasing MMP-2 expression, depending on FPR/MAPK/STAT3 activation pathways." (PMID 36766767, 2023). "To further elucidate the regulatory mechanism of GDF15 in melanoma cells, we first measured the expression of GDF15 in STAT3-silenced cells and found that the expression of GDF15 in STAT3-silenced cells was significantly reduced compared with that in control cells." (PMID 36720918, 2023).
melanoma (continued). "Microglia cells were treated with MCM from the four melanoma cell lines together with inhibitors for STAT3 (targeting Ser727, but not the Tyr705 residue)—which is downstream to JAK activation, JAK, JNK or MEK/ERK for 3 h." (PMID 37894348, 2023). "In melanoma, NIC inhibits p-STAT3 expression, thus inhibiting lung metastasis in melanoma." (PMID 36555754, 2022). "could be an adjunctive therapy for melanoma due to its high content of polyphenols and their inhibitory effect on the proliferation of B6F10 cells via the inhibition of STAT3 and the induction of apoptosis." (PMID 35409218, 2022). "To explore whether STAT3 contributes to EEF2K‐mediated melanoma progression, we further evaluated the effect of EEF2K on melanoma cells in the presence of stattic." (PMID 35184394, 2022). "EEF2K/p‐STAT3/SPP1 may be a novel oncogenic pathway in melanoma progression, which could be a target for novel combination therapy for melanoma." (PMID 35184394, 2022). "Therefore, we suggest that DHA suppressed melanoma invasiveness by reducing MMPs and EMT activity and expression through inhibiting the constitutive activities STAT3/NF-κB and accelerating the STAT1." (PMID 34539408, 2021). "Taken together, the data with WM115, WM793, WM1158, SK-MEL-28 melanoma cell lines support the conclusion that elevated S100B negatively regulates IL6 expression and its downstream signaling as measured via phosphorylation of STAT3." (PMID 34411141, 2021). "To date, several STAT3 inhibitors have been tested and demonstrated promising results in early-phase clinical trials, but none of them has been approved for melanoma treatment due to adverse side effects and toxicity." (PMID 34208965, 2021). "Furthermore, flow cytometric analysis demonstrated that STAT3 inhibitor with PD-1 treatment weakened the secretion of TGF-β and IL-10 on Treg cells compared to anti-PD-1-treated melanoma mice, implying an enhanced anti-tumor immunity." (PMID 33936081, 2021). "Indeed, the elevated S100B levels in malignant melanoma cell lines correspond to low levels of IL6 and p-STAT3." (PMID 34411141, 2021). "Our findings reveal that enforced PEAK1 could activate JAK/STAT3 signal and promote EMT in melanoma cells." (PMID 34365903, 2021). "G6PD may be regulated apoptosis and expression of cell cycle–related proteins through phosphorylation of transcription factors STAT3 and STAT5, thus mediating formation and growth of human melanoma cells." (PMID 33630390, 2021). "Importantly, the significance of STAT-3 and PTEN signaling pathways are well acknowledged in melanoma progression." (PMID 35011682, 2021). "Interestingly, depletion of STAT3 in the preclinical model dampened the tumor growth and Treg cells recruitment and increased the CD8+/CD4+ ratio in melanoma." (PMID 33936081, 2021). "The level of phosphorylation of STAT3 is higher in metastasis (particularly the brain and lung) than in cutaneous primary melanomas and is a negative prognostic factor for overall survival in patients who did not develop central nervous system metastasis." (PMID 34680615, 2021). "Collectively, these results proved the regulatory role of CD27-AS1-208 in STAT3 signaling and PP2A activity in melanoma cells, implying that CD27-AS1-208 might exert its facilitative role through STAT3 pathway or/and PP2A activity." (PMID 35096622, 2021). "Additionally, using melanoma cell line A375, growth was inhibited by IL6 in a STAT3-specific manner." (PMID 34411141, 2021). "STAT3 was shown to repress MITF and reduces the proliferation of melanoma cells." (PMID 34638912, 2021). "The expression of IGF1 mediated upregulation of FGFR3 and STAT3 in both TAB and melanoma cells." (PMID 34830951, 2021). "Moreover, in case of human melanoma cell lines A375, 518A2, and G361, API (40 μM) inhibited in a dose-dependent manner the expression levels of STAT3." (PMID 34239802, 2021).